STAT1 (signal transducer and activator of transcription 1)
Diseases named in the same sentence as STAT1 in open-access papers (continued):
Sharing a sentence is not in itself a finding about the gene and the disease.
breast cancer (continued). "It is well-known that STAT3 and to some extent STAT1 is activated in breast cancers and that constitutively active mutants of STAT3 promote the growth and survival of tumor cells thereby contributing to malignancy." (PMID 19338666, 2009). "It is well-known that STAT3 and to some extent STAT1 is activated in breast cancers and that constitutively active mutants of STAT3 promotes the growth and survival of tumor cells thereby contributing to malignancy." (PMID 19338666, 2009). "Up-regulation of STAT1 has been reported in breast cancer micrometastasis in the bone marrow, suggesting a more metastasis-prone phenotype." (PMID 17868458, 2007). "IFN-gamma is a potent activator of STAT1 and activated, phosphorylated STAT1 has been correlated to a good prognosis in breast cancer." (PMID 17986321, 2007). "Another interesting example is TINCR, which is activated by IFN-γ/STAT1 signaling in breast cancer." (PMID 41154428, 2025). "We previously demonstrated that TTI-101 targets STAT1, in addition to STAT3, in human radioresistant head and neck squamous cell carcinoma cell lines and that it also targets STAT5 in a mouse model of increased breast cancer risk caused by pregnancy." (PMID 41226842, 2025). "STAT1 has been recognized as regulator of p21 expression through the FGFR pathway in breast cancer." (PMID 38553760, 2024). "STAT1 mediates the growth-inhibitory effect of FGF4 in a breast cancer cell line." (PMID 38553760, 2024). "STAT1 transcriptionally activates ERα expression to accelerate breast cancer development." (PMID 38764020, 2024). "Hence, the mechanism by which EPS exerts these effects on breast cancer cells is most likely through activation of IKKβ-NFκB signaling and possibly also STAT1 activation as shown in our current model." (PMID 38074643, 2023). "CircRPPH1 could act as an oncogene and regulate the progression of breast cancer via the circRPPH1-miR-512-5p-STAT1 axis." (PMID 37298501, 2023). "In addition, STAT1 depletion in CAFs reduced periductal reactive fibrosis and retarded the progression of early breast cancer in vivo, suggesting that STAT1 contributes to tumorigenesis from the stroma." (PMID 37496657, 2023). "In addition, a recent bioinformatics study demonstrated the potential significance of the STAT1/ESCO2 pathway in breast cancer." (PMID 37968576, 2023). "Hsa_circ_0086735-miR-1296-5p-STAT1 axis may serve as therapeutic considerations to eradicate tamoxifen -resistance in breast cancer." (PMID 37187897, 2023). "STAT1/c-Myc pathway is involved in POR-induced TAM-resistant breast cancer." (PMID 37187897, 2023). "To explore the mechanism of MLN8237 promoting PD-L1 expression, we screened JAK/STAT, PI3K/AKT and MAPK/ERK signal paths with SKBR3 breast cancer cells, and the protein levels of p-STAT1, p-STAT3, p-STAT5, p-AKT and p-ERK were detected after treatment with MLN8237." (PMID 37781397, 2023). "Notably the breast cancer tumor suppressor and interferon-regulated transcription factor STAT1 is most strongly co-expressed with RHAMM in these data sets (TCGA pan-cancer atlas shown)." (PMID 37349798, 2023). "Next, we asked if the inhibitor’s effects on TILs and anti-tumor immunity in AT3-OVA mammary tumors might nonetheless occur as a consequence of enhanced intratumoral T cell activation and resultant inflammatory STAT-1 signaling in tumors." (PMID 37500611, 2023). "To follow up on our previous findings demonstrating the key roles of STAT3 and STAT1 in mediating the cell-autonomous pro-metastatic effects of PD-L1 in breast cancer cells, we next determined the impact of each of the four N-linked glycosylation sites on STAT3 and STAT1 activation." (PMID 37830552, 2023). "Moreover, dysregulated STAT1 activation\expression has been shown to assist the cancer cell immune escape and contribute to unfavorable prognosis in breast cancer." (PMID 37968576, 2023).
breast cancer (continued). "More specifically in the context of CIN, drugs or genetic drivers that decrease mitotic fidelity have been found to lead to activation of STAT1 signaling, indicated by increased levels of phosphorylated STAT1 in various cancer types, including breast cancer and acute myeloid leukemia." (PMID 37561163, 2023). "Finally, the obtained hsa_circ_0086735-miR-1296-5p-STAT1 was proved to promote the progression of luminal breast cancer and tamoxifen resistance." (PMID 37187897, 2023). "Therefore, the hsa_circ_0086735-miR-1296-5p-STAT1 axis can promote the cell proliferation and inhibited cell apoptosis of luminal-subtype breast cancer." (PMID 37187897, 2023). "Here, to follow up on observations showing that PD-L1 is N-linked glycosylated in breast cancer patient samples, it is important to validate the connections between the STAT3 and STAT1 proteins with the N-linked glycosylation status of PD-L1 in breast cancer patients and in mice tumor samples." (PMID 37830552, 2023). "Surprisingly, STAT1 ranked first in both breast cancer and ovarian cancer, implying that there might be a strong correlation between STAT1 and GCH1." (PMID 36793373, 2023). "Furthermore, constitutive type I IFN downstream signaling, e.g., via pSTAT1, correlates with invasiveness of breast cancer in humans as well as shorter survival of mice implanted with mouse mammary carcinoma cells overexpressing an active form of STAT1." (PMID 36571986, 2023). "The anti-tumor function of STAT1 could be restored by forced expression in breast cancer cells derived from STAT null mice and injected into null mice." (PMID 35681772, 2022). "STAT1 expression is transcriptionally upregulated by HER2 in breast cancer cells." (PMID 35781872, 2022). "DNMT3B is known to influence breast cancer development via regulation of the STAT1/FOXO1 pathway." (PMID 36061358, 2022). "STAT1 encodes a protein that serves tumor-suppressive functions in many cancers and has been recognized as a potential biomarker for patient selection for treatment with anti-PD-1/anti-PD-L1 antibodies in breast cancer, as p-STAT1 correlates with higher PD-L1 and HLA class I expression." (PMID 35892849, 2022). "However, STAT1 can promote the progression of tumors in pleural mesothelioma, breast cancer and head and neck cancer." (PMID 35515130, 2022). "We next tested whether therapies that stimulate STAT1-mediated inflammatory responses may increase the therapeutic efficacy of phenformin in breast cancer." (PMID 34083537, 2021). "It has been suggested that Que may improve the progression of breast cancer from precancerous lesions to breast cancer or improve the prognosis of breast cancer patients through the JAK/STAT1 signaling pathway." (PMID 34838003, 2021). "Coupled with our observations that loss of pY313-dependent ShcA signaling increases STAT1 expression in breast cancer cells 29, we considered the possibility that STAT1 may increase phenformin sensitivity." (PMID 34083537, 2021). "Indeed, IFN/STAT1 activation in individual HER2+ breast cancers can exert opposing effects on their sensitivity to HER2 kinase inhibitors." (PMID 33807608, 2021). "In this study, we investigated the effect of Que on γδ T immune cells or its inhibitory effect on breast cancer cells and explored the immunomodulatory function of Que through the JAK/STAT1 signaling pathway and the underlying mechanisms of its synergistic killing of breast cancer cells." (PMID 34838003, 2021). "Candidate pathways were constructed starting from the estrogen receptor ESR1 gene and targeting breast cancer-associated transcription factors, such as JUN, FOS, STAT1, STAT3, STAT5A, ELK1, and ETS1 (Target transcription factors were pre-identified by GibbsOS19)." (PMID 33432018, 2021).
breast cancer (continued). "Additional studies confirmed the effects of radiation on STAT1-expression in breast cancer, gliosarcoma, and metastatic PCa cell lines, where STAT1 was significantly up-regulated after radiation, indicating a universal role of STAT1 in radioresistance, including PCa." (PMID 34638338, 2021). "Que-related pathways included the JAK/STAT1 pathway, suggesting that Que may improve the progression of breast cancer from precancerous lesions to breast cancer or improve the prognosis of breast cancer patients through the JAK/STAT1 signaling pathway." (PMID 34838003, 2021). "Thus, IFNγ sensitizes multiple breast cancer cell lines, spanning distinct molecular subtypes, to phenformin in a STAT1-dependent manner." (PMID 34083537, 2021). "Thus, oxidative stress underlies the synergistic effects of phenformin and IFNγ-driven STAT1 activation in potentiating breast cancer cell death." (PMID 34083537, 2021). "Moreover, IFNγ modestly decreased the metabolic flexibility of MT4788 breast cancer cells in a STAT1-dependent manner." (PMID 34083537, 2021). "In addition, correlation analysis from bc-GenExMiner v4.5 revealed that the expression of HDAC2, as well as JAK1, JAK2, and STAT1, was significantly correlated with that of PD-L1 in breast cancer." (PMID 34365463, 2021). "JAK2 knockdown (KD) in human acute myelogenous leukemia (AML) cell line, STAT1 KD in human T cell acute lymphocytic leukemia cells, Stat3 KD in mouse mammary tumor, and STAT3 KD in human urothelial cancer cells resulted in zero to two OCRG upregulation and one to five OCRG downregulations." (PMID 34368262, 2021). "It induces of breast cancer progression by activating STAT1 and STAT3." (PMID 34488773, 2021). "However, studies have also shown that high STAT1 mRNA levels correlated with poor prognosis in breast cancer, while high levels of STAT1 activity promoted cell growth and immune suppression in breast cancer." (PMID 34276757, 2021). "STAT1 drives aromatase inhibitor resistance in breast cancer, and is highly expressed in estrogen receptor-positive, tamoxifen-resistant breast cancer cell lines, indicating it may be a promising target in this malignancy." (PMID 33521321, 2020). "In breast cancer, correlations with good and poor prognosis have been reported for STAT1 expression, and high protein expression of STAT1 together with high levels of CD74 defined a subtype of triple negative breast cancer with increased invasiveness and metastatic potential." (PMID 32275681, 2020). "Moreover, cell sorting of MCF-7 breast cancer cells using the stem marker CD44 revealed that CD44+ cells had higher levels of STAT1 expression than CD44− cells." (PMID 32296435, 2020). "Additionally, our previous study revealed that IFN-β secreted by ASCs mediates cell cytotoxicity through JAK/STAT1 pathway in breast cancer cells." (PMID 32210710, 2020). "A recent study showed that STAT1 promoted breast cancer progression by increasing CSC properties." (PMID 32292520, 2020). "Importantly, analysis of basal-like breast cancer patient samples exhibited an inverse relationship between STAT1 and Ras/MAPK activation signatures." (PMID 33062958, 2020). "Our results indicate that STATs family play a significantly prognostic role in breast cancer patients and individual STATs, except STAT1 and STAT2, and may be a favorable prognostic biomarker in breast cancer." (PMID 29326301, 2018). "However, it is unclear that TIMP3 inhibits the progress of breast cancer via the FOXO1/STAT1 pathway." (PMID 29796115, 2018). "Stromal STAT1 expression promotes tumor progression in breast cancer." (PMID 30237810, 2018). "In the present study, STAT1/IRF9 expression in breast cancer samples was analysed." (PMID 30334368, 2018). "Finally, our results showed that miR-29c exerted its function in breast cancers by regulating the TIMP3/STAT1/FOXO1 pathway." (PMID 29796115, 2018).
breast cancer (continued). "Upregulated DNMT3B is critical for promoter methylation and decreased expression of TIMP3, which could promote progression of breast cancer via the TIMP3/STAT1/FOXO1 pathway." (PMID 29796115, 2018). "STAT2, STAT4, STAT5a, STAT5b, and STAT6 had significantly favorable effect on RFS of breast cancer patients, but STAT1 had significant worse effect on RFS; STAT5b had significant favorable effect on PPS, while, STAT2 had significant worse effect on PPS for breast cancer patients." (PMID 29326301, 2018). "A decrease or loss of STAT1 signaling activity has been reported in many types of cancer, such as colon cancer, breast cancer, leukemia, and melanoma and a correlation between the high expression of STAT1 and good prognosis has been observed in colorectal, pancreatic, and esophageal cancers." (PMID 30235866, 2018). "Inhibition of STAT1 signaling reduced the primary growth and progression of breast cancer cells." (PMID 29796115, 2018). "Therefore, we sought to define the functional role of STAT1 downstream of EGFR activation in metastatic breast cancer cells." (PMID 30250119, 2018). "STAT1 can promote the growth of breast cancer by inhibiting immunity." (PMID 29796115, 2018). "Targeting of STAT1 is a potential treatment strategy for endocrine‐resistant breast cancers." (PMID 30334368, 2018). "Chromatin immunoprecipitation revealed that ERα transcription is associated with STAT1 recruitment to the ERα promoter region, suggesting that transcriptional regulation is one mechanism by which STAT1 regulates ERα mRNA levels and ERα signalling in breast cancer cells." (PMID 30334368, 2018). "In addition, levels of ACTA2 and STAT1 expression were highly expressed in HER2-positive breast cancers." (PMID 28881584, 2017). "Thus, chronic STAT1 activation in breast cancer cells selects for the activation of compensatory immunosuppressive signals." (PMID 28276425, 2017). "We found that HER2 overexpression increases levels of ACTA2 and STAT1 in breast cancer cells." (PMID 28881584, 2017). "Indeed, tyrosine kinase inhibitors will impair both Y239/240 and Y313-ShcA phosphorylation to limit STAT3 immunosuppressive signals and activate STAT1 in breast cancer cells." (PMID 28276425, 2017). "We found that p38 was activated in MCF-7 cells with CM-CAFs treatment, however, in the CM-CAFs/miR-29b or STAT1 is one of down-stream transcriptional factor of p38 and it was also inhibited in the breast cancer cells with CM-CAFs/miR-29b or CM-CAFs/miR-29b treatment." (PMID 28465475, 2017). "ACTA2 and STAT1 expression was also increased in HER2-positive breast cancer patients." (PMID 28881584, 2017). "However, numerous studies also suggest that STAT1 induces tumour intrinsic and stromal gene expression changes that promote breast cancer development." (PMID 28276425, 2017). "However, the mRNA level of STAT1 was significantly up-regulated in breast cancer, and increased in higher SBR grade, which predicted fast-growing, spreading tumors." (PMID 28422733, 2017). "Increased STAT1 expression and high STAT1 activation (p-STAT1 protein levels) were related to a favorable prognosis in colorectal carcinoma, oral squamous cell carcinoma, as well as in breast cancer." (PMID 28536310, 2017). "In this study we have used SSM2 and SSM3 ERα+/PR+ murine cell lines derived from spontaneous breast carcinomas in mice lacking STAT1, a transcription factor associated with tumor progression in ERα+ breast cancer patients." (PMID 27391074, 2016). "Therefore, given that clinical trials evaluating Il-6/JAK/ STAT inhibitors in breast cancer patients are under way, it would be important to determine the role of STAT1 and STAT3 in this disease." (PMID 27769057, 2016). "Indeed, tumor suppressive functions of STAT1 were associated with positive prognosis in CRC and breast cancer." (PMID 27191495, 2016). "Furthermore, STAT1 has been reported to inhibit the development of mammary tumours in experimental models." (PMID 27769057, 2016).
breast cancer (continued). "In our study, we demonstrated that several ISGs including IFITM1, STAT1 and PLSCR1 and their encoded proteins are constitutively overexpressed in AI-resistant breast cancer cells and AI-resistant tumors and that their overexpression provides a survival advantage in the resistant cells." (PMID 25588716, 2015). "In conclusion, these results indicate that STAT1 expression and activation can be increased in endocrine-resistant breast cancer and STAT1 inhibitors may be effective in resistant cells." (PMID 24728078, 2014). "In breast cancer, the increase in estrogen levels leads to a higher expression of STAT1 gene." (PMID 24270600, 2014). "Expression of PR was also very strongly associated with STAT1 in the primary breast cancers (p<0.0001) although not in nodal disease." (PMID 24728078, 2014). "The anti-proliferative effect of EGCG in the resistant lines suggested that STAT1 might be important in the development of resistant breast cancer." (PMID 24728078, 2014). "Furthermore, increased expression of genes belonging to the so-called interferon-related gene signature including STAT1 was shown to correlate with elevated frequency of relapse in human breast cancer." (PMID 24725474, 2014). "However, the underlying mechanisms for E2-ERα inhibition of CIITA transactivation and STAT1 signaling in breast cancer are likely to be more diverse and complex." (PMID 24475282, 2014). "When lymph node expression was compared to its paired primary breast cancer expression, there was greater expression of cytoplasmic STAT1 (∼3.1 fold), phospho-STAT3(Ser727) (∼1.8 fold), and STAT5 (∼1.5 fold) and nuclear phospho-STAT3(Ser727) (∼1.5 fold) in the nodes." (PMID 24728078, 2014). "However, in breast cancer data from microarray analysis indicated a predictive value of high mRNA expression levels of STAT1 and STAT1 target genes belonging to the interferon-related signature for a poor response to therapy." (PMID 24725474, 2014). "This notion is supported by immunohistochemical (IHC) analysis of STAT1 expression in estrogen receptor (ER) - positive primary mammary carcinomas, which revealed lower STAT1 expression levels in the tumor epithelium as compared to the adjacent normal epithelium in a considerable number of cases." (PMID 24725474, 2014). "Stat1 showed significant variation of expression across breast cancer samples." (PMID 23520493, 2013). "Our data suggest that several pathway members, such as Stat1, Ifngr2, Tgtp1, Ifit1, Gbp1 and Gbp3, may be suitable biomarkers for residual disease in breast cancer patients treated with cytotoxic chemotherapy." (PMID 23520493, 2013). "In addition, the molecular signature of the STAT1-/- mammary tumors overlaps closely to that of human luminal breast cancers." (PMID 22264274, 2012). "We first investigated whether enforced expression of STAT1 in STAT1-/- mammary tumor cells affected their tumorigenic phenotype." (PMID 22264274, 2012). "It is tempting to speculate that the tumor-initiating cells in the STAT1-/- mammary tumors reside in the luminal epithelial subset because of the significant expansion of these cells in the preneoplastic lesions." (PMID 22264274, 2012). "Having demonstrated that the STAT1-/- ERα+ mammary tumor cells required ovarian hormones for establishment of tumor growth, we next examined whether these tumors also depended on ovarian hormones to maintain tumor progression." (PMID 22264274, 2012). "However, these hormone-independent cells are extremely rare in the primary STAT1-/- mammary tumors as demonstrated by the fact that tumor fragments from two independent primary tumors failed to engraft in ovariectomized mice." (PMID 22264274, 2012). "Most recently, in vivo studies indicated that STAT1 could suppress tumor development in the ErbB2/Neu-driven mammary tumor models, although its action in other types of mammary tumors remains undefined." (PMID 22264274, 2012).